TNF (tumor necrosis factor)
Diseases named in the same sentence as TNF in open-access papers (continued):
Sharing a sentence is not in itself a finding about the gene and the disease.
viral infection (continued). "Like IFNγ, TNFα plays a critical role in the control of viral infections including enhanced antigen presentation, recruitment of leukocytes, apoptosis of infected cells, a direct antiviral effect, and polarization of TH cell responses." (PMID 37866114, 2023). "It is also well-established that the Th1-polarized immune response mediates viral infection control via IFNγ and TNFα cytokine production, ensuring efficient viral clearance." (PMID 37511205, 2023). "In particular, they observed increased levels of proinflammatory cytokines IL-6 and TNFα in Peli1 knockout mice upon viral infection." (PMID 37296648, 2023). "Next, to understand the importance of the TNFα/TNFR2 axis in the antiviral activity of NK cells in virus infection, we compared cell proportions, activation, and metabolic states of NK cells from wild-type and TNFR2 KO mice on D4 post-MCMV infection." (PMID 37553427, 2023). "We found that both doses significantly reduced the release of inflammatory cytokines (TNFα, IL-6, and IL-1β), induced by virus infection." (PMID 37108306, 2023). "In C57BL/6 mice, viral infection induced tissue damage and the expression of IL-4, TNF-α, and IFN-γ in the lungs, which were alleviated following the treatment of berberine." (PMID 37089926, 2023). "CH was shown to reduce the secretion and intracellular expression of TNF-α and IL-6, which are inflammatory cytokines that increase after viral infection." (PMID 37711616, 2023). "Meanwhile, the suppression of protein levels of NF-κB p65, TNF-α, and IL-1β were observed, whereas viral infection induced the expression of these proteins." (PMID 37089926, 2023). "Under virus infection, which promotes Ripk1-dependent necrosis by stimulating tumor necrosis factor (TNF), Ripk3 subsequently induced the phosphorylation of Ripk1, which resulted in the formation of a pro-necrotic necrosome complex." (PMID 36849513, 2023). "It has been reported that the type I IFN signaling pathway and TNF signaling pathway trigger pyroptosis to initiate proinflammatory responses against virus infection." (PMID 37202386, 2023). "During an immune response, NK cells produce chemokines, as well as cytokines, including interferon-gamma (IFN-γ) and tumor necrosis factor-alpha (TNF-α), which are important for host protection against viral infection and tumor formation." (PMID 37445721, 2023). "Emodin was able to combat viral infection by regulating the levels of the cytokines TNF-α, IFN-γ, IL-6, and IL-4 in the sera of infected mice." (PMID 37764342, 2023). "The mRNA levels of IL-1β, IL-6, and IL-8 showed a trend of decreases and then increases, while the mRNA levels of TNF-α and IL-10 significantly increased after viral infection." (PMID 36995259, 2023). "Resident NK cells acquire cytolytic functions mediated through TNFα and granzyme B during hepatotropic viral infections, cirrhotic pathology, and HCC (Sällberg and Pasetto, 2020)." (PMID 36656749, 2023). "In the NF-κB canonical pathway activated by TNF-α, IL-1, or byproducts of bacterial (i.e., LPS) or viral infection, NF-κB promotes the expression of COX2 and MIP-1β." (PMID 36839217, 2023). "Elevated release of interleukin(IL)-6, IL-7, and tumor necrosis factor (TNF) have been recorded as the consequence of innate immune response upon the viral infection." (PMID 37456016, 2023). "The protective role of TNF-α in viral infections raises concerns about TNF antagonists for the treatment of patients with CHIKV during the acute phase." (PMID 37014125, 2023). "The UVA-induced upregulated DEGs were mostly enriched in virus infection (herpes simplex virus 1 infection), while the downregulated DEGs were significantly enriched in the TNF signaling pathway and IL-17 signaling pathway." (PMID 36832881, 2023). "Viral infection triggers rapid TNF production by the innate immune system through activation of the nuclear factor-kappa B (NF-κB) signaling pathway." (PMID 36851532, 2023).
viral infection (continued). "Inhibiting USP14 in turn results in RIG-I-triggered TNF-α and IL-6 production in mice with virus infection." (PMID 37658402, 2023). "Viral infection triggers an extensive cytokine response, such as IL-1, IL-2, IL-6, TNF-α, IFN-γ, IFN-induced protein 10 kDa and so on." (PMID 38027806, 2023). "TNF, a proinflammatory cytokine produced during viral infection, can stimulate monocytes to secrete MMPs." (PMID 36311773, 2022). "The results of the KEGG pathway enrichment analysis show that the targets of CQQN are mainly concentrated in virus infection and TNF, IL-17, and cancer pathways." (PMID 35528163, 2022). "The biologic therapies often target TNF-α which plays a critical role in the control of viral infection since it is involved in recruiting and activating macrophages, Natural Killer, T cells, and antigen presenting cells." (PMID 35449072, 2022). "About the therapy with azathioprine, methotrexate, anti-TNF, and tofacitinib, the International Organization for the Study of IBD (IOIBD) is doubtful if it would pose a significant risk for the viral infection." (PMID 36406478, 2022). "Necroptosis is a regulated caspase-independent form of cell death that is stimulated by viral infection and tumor necrosis factor (TNF) signaling." (PMID 39872359, 2022). "Their results showed that IL-6 and TNFα were higher in bacterial infections compared to viral infections and elevated cytokine concentrations dropped within three days of antibiotic therapy." (PMID 35500008, 2022). "NF-κB and P38 MAPK are critical regulators involved in the regulation of proinflammatory cytokines, which can be activated by viral infection or several cytokines (e.g., TNF-α and IL-1β)." (PMID 36180831, 2022). "This is mainly attributed to cytokines produced in viral infections that block Tumor Necrosis Factor TNF-a production." (PMID 36295492, 2022). "In response to most viral infections, B cells can bind to viral proteins through their antigen receptors, by secreting effector molecules (IL-2, IL-4, IL-6, IFN-γ, TNF-α) to help contain viral infections." (PMID 35774402, 2022). "Shared down‐regulated genes by CEN and CO were mainly enriched in apoptosis, TNF signaling pathway and various virus infection pathway." (PMID 36354175, 2022). "Among them, pI3K-Akt signaling pathway, MAPK signaling pathway, Ras signaling pathway and TNF signaling pathway have been proved to be related to virus infection." (PMID 35831876, 2022). "Pro-inflammatory cytokines, such as interleukin-6 (IL-6) and tumor necrosis factor-alpha (TNF-α) produced under viral infections, can exacerbate the severity of illness, resulting in poor prognosis, including cytokine storms." (PMID 35062284, 2022). "Our research provides evidence that endogenous TNF-α can be used as a strategy to encounter viral infections." (PMID 35268699, 2022). "It is known that TNF-α expression in lung epithelial cells is higher during influenza and viral infections." (PMID 36615820, 2022). "Various proinflammatory stimuli, such as viral infections, lipopolysaccharide, tumor necrosis factor-α (TNF-α), interferon-γ, and interleukin-1β (IL-1β), can induce the expression of CCL3." (PMID 35744024, 2022). "KEGG analysis showed that the relevant YQJPR signaling pathways in the treatment of COPD included virus infection, TNF, IL-17, HIF-1, MAPK, AGE-RAGE, and cancer pathways." (PMID 36118092, 2022). "Further, LITAF is involved in the immune response against bacterial and viral infections and can regulate TNF-α transcription, inflammation, proliferation, and apoptosis." (PMID 36140805, 2022). "KYOTO ENCYCLOPEDIA OF GENES AND GENOMES pathway enrichment among these genes showed that they were mainly enriched in terms of “TNF signaling pathway”, “Hepatitis” and “virus infection”, which were also reported to related to renal fibrosis or ECM deposition." (PMID 35246505, 2022).
viral infection (continued). "TNF-α plays a role in the inflammatory response locally and in the blood and is essential for the early response to viral infection by promoting lymphocyte infiltration." (PMID 35492705, 2022). "The activation of NF-κB in viral infection induces gene expression of a wide range of cytokines (e.g., IL-1, IL-2, IL-6, IL-12, TNF-α, LT-α, LT-β, and GM-CSF), and chemokines (e.g., IL-8, MIP-1, MCP1, RANTES, and eotaxin)." (PMID 35967323, 2022). "To determine how TNFα-mediated glycolytic activation contributes to its ability to induce the anti-viral state, we assessed how glycolytic inhibition impacted TNFα’s ability to limit viral infection of the laboratory strain of HCMV, AD169." (PMID 35834576, 2022). "Additional to the lack of knowledge about what side effects can leave the use of TNF immune modulators in viral infections." (PMID 35631442, 2022). "The increase in IL-1β, IL-6, IL-4, and TNF-α expression in the spleen indicates the activation of the immune system, resulting in resistance to virus and prevention of virus infection." (PMID 36177044, 2022). "Lastly, viral infection elicits the production of TNF that can act in an autocrine/paracrine manner to initiate apoptosis in the presence of functional caspase-8, or necroptosis via the association of RIPK1 with RIPK3 in its absence." (PMID 35549723, 2022). "To investigate their effect on cytokines expression, we used two PAMs with high and low initial TNF expression levels for viral infection, and found that both PAMs had similar cytokines expression trends after infection with ASFV." (PMID 36544767, 2022). "For instance, during the acute inflammatory response to a virus infection, the body releases the cytokines TNF-α, IL-1, and IL-6, which act on fibroblasts and endothelial cells, hence increasing vascular permeability." (PMID 35755996, 2022). "TNF plays a critical role in controlling viral infections by recruiting and activating macrophages, T cells, and antigen-presenting cells." (PMID 35060934, 2022). "NK cells, stimulated by inflammatory cytokines such as INF-γ, and TNF-α, are critical in the innate and adaptive immune response to intracellular stress, tumor, or viral infection." (PMID 36060967, 2022). "Most NK and T cell ligands display structural similarities and belong to a few protein families including cadherins, collagen, C-type lectin, TNF, HLA and immunoglobulin and often these are modulated during viral infection." (PMID 35727847, 2022). "Several KEGG and Reactome terms related to the immune system, TNFα and interferon signaling, and virus infection were significantly enriched pathways." (PMID 35578269, 2022). "KEGG enrichment showed that they were involved in disorders caused by a viral infection, NOD-like receptor signaling pathway, TNF signaling pathway, RIG-I-like receptor signaling pathway, Toll-like receptor signaling pathway, JAK-STAT signaling pathway." (PMID 36341359, 2022). "KEGG analysis showed that the relevant CQQN signaling pathways in the treatment of pharyngitis included virus infection, TNF, IL-17, and cancer pathways." (PMID 35528163, 2022). "Pro-inflammatory cytokines, such as IL-6, IL-1β, and TNF-α, are significantly increased during viral infections and exacerbate lung tissue damage." (PMID 36147321, 2022). "During lipopolysaccharide (LPS) stimulation, virus infection, inflammation, and tissue injury, endothelial cells can secrete a high level of chemokines and cytokines, such as tumor necrosis factor α (TNF-α) and interleukin-1 (IL-1)." (PMID 35336858, 2022). "In the acute inflammatory response phase to viral infection, an early increase in serum IL-1β and TNF-α levels are observed within the first 30 min, followed by a rise in IL-6 levels." (PMID 35888173, 2022).
viral infection (continued). "The majority of DEGs focus on disorders caused by viral infections, NOD-like receptor signaling pathway, TNF signaling pathway, RIG-I-like receptor signaling pathway, Toll-like receptor signaling pathway, JAK-STAT signaling pathway." (PMID 36341359, 2022). "Cytotoxic effector genes (GZMA, GZMB, ID2, and PLAC8) were enriched in Δ382 SARS-CoV-2 infected patients, coupled with high plasma levels of IFN-γ, TNF-α, and IL-2 during the acute phase of virus infection." (PMID 34716845, 2022). "During viral infection, virus-induced inflammation leads to systemic or local production of cytokines, such as interleukin-6 (IL-6), tumor necrosis factor-α (TNF-α), interferon (IFN) and monocyte chemoattractant protein 1 (MCP-1)." (PMID 36303865, 2022). "The pro-inflammatory activity of astrocytes can be induced to high levels by IL-1β and TNFα and viral infections, e.g., HIV, to facilitate an immune response." (PMID 35448516, 2022). "Proinflammatory cytokines, including TNF-α and IL-1β, can be robustly induced after viral infection." (PMID 36359059, 2022). "NF-κB activation in patients with COPD occurs in response to inflammatory mediators such as IL-1β and TNF-α or due to activation of Toll-like receptors (TLRs) following bacterial or viral infections." (PMID 35517806, 2022). "As expected, the relative expression of these three viral infection–induced secretion of cytokines TNF-α (except 0.004%), ISG56 and IL-8 were dramatically down-regulated by TTO treatment in VSV preinfection modes." (PMID 34869732, 2021). "Proinflammatory cytokines, such as TNF-α and IL-1β, readily detected in the trachea and lung in BoHV-1-infected cattle, contributes greatly to virus infection-induced rhinotracheitis and pneumonia." (PMID 34008469, 2021). "TNF is a cytokine that, among many functions, has pro-inflammatory effects during a viral infection." (PMID 33672623, 2021). "Activation of NF-κB by TNF-α, IL-1 or by-products of bacterial and viral infection is an exemplary pathway." (PMID 33678123, 2021). "Viral infections can activate NK cells to produce IFNγ, TNFα, and other immunity-enhancing mediators that prime the adaptive immune response." (PMID 35003077, 2021). "Taking respiratory syncytial virus and influenza as examples, gut microbiota was significantly altered by viral infections itself and multifactorial variables, such as inflammation-induced tumor necrosis factor-alpha (TNF-α)." (PMID 34442684, 2021). "IL-6 is a highly inducible pro-inflammatory cytokine secreted by several cell types including monocytes, lymphocytes, fibroblasts and endothelial cells; interleukin-1β (IL-1β) and TNF-α, viral infection and Angiotensin II are able to induce IL-6." (PMID 34001199, 2021). "NK cells that are characterized by cytokine production, including IFN-γ and TNF-α, are an important defense against virus infections." (PMID 35062250, 2021). "In this sense, the analysis of the specific contribution to mousepox pathogenesis of CRDs and SECRET domains from CrmD revealed that chemokines and TNF cooperate during virus infection to develop the inflammatory response and provide anti-viral immunity." (PMID 34451529, 2021). "In viral infection, cell death-induction through TNF seems to be an important facet of its pleiotropic signaling qualities." (PMID 34711816, 2021). "The average concentrations of TNF quantified in blood or serum during viral infection are on the lower end of the range we used in our in vitro experiments." (PMID 34016976, 2021). "Virus infections result in an inflammatory environment with an increased IL-15 and TNFα and the subsequent recruiting of antigen-presenting cells to the infection site, leading to the induction of an adaptive immune response." (PMID 34211465, 2021).
viral infection (continued). "While, TNF-α which is a marker of viral infection, stimulates T-lymphocytes to produce a variety of inflammatory factors, thereby promoting the occurrence of inflammatory reactions, and their expression also tends to increase at 5–7 dpi." (PMID 34249779, 2021). "Our systems biology results highlighted central signaling roles for IFN-gamma and TNF-alpha in both myocarditis and viral disease maps." (PMID 34696294, 2021). "Cardiac TNF-α abundance during viral infection has been observed to correlate with reduced cardiac function in humans, and mouse models have demonstrated a causal role for TNF-α in virus-induced cardiac pathology." (PMID 34696354, 2021). "Our data show that TNF dramatically shortens the decision latency specifically following viral infection." (PMID 34016976, 2021). "It is noteworthy that these cytokines, which include tumor necrosis factor alpha (TNF-α) and interleukin 1β (IL-1β), play a critical role in triggering acute-phase responses to viral infection." (PMID 33802995, 2021). "TNFα is a macrophage derived cytokine that is well established to play an important role in the control of viral infection, which are common post-transplantation." (PMID 35126353, 2021). "The key takeaway from our paper is that TNF modulates the speed of cell death during viral infection to restrict viral spread." (PMID 34016976, 2021). "TNF was also measured because this cytokine is essential for the control of the viral infection by macrophages." (PMID 34268134, 2021). "Tα1 was shown to promote DCs to secrete inflammatory cytokines, such as TNF-α, IL-6, and IL-8, in response to viral infection." (PMID 34408744, 2021). "The expression of genes related to these pathways, such as TNF-α, IL-6 and IL-8, was altered during viral infection." (PMID 34887856, 2021). "In general, when a clinically detectable viral infection is present, elevated concentrations of cytokines, including IL-6, IL-1, IL-8, and TNF-α in amniotic fluid or cervicovaginal lavage of patients, is predictive of the onset of preterm labour." (PMID 34835071, 2021). "Its secretion is induced by IL-1β, interferons, tumor necrosis factor-α (TNF-α), lipopolysaccharide, and viral infections." (PMID 34501305, 2021). "On the other hand, tumor necrosis factor alpha is secreted in response to viral infections and has a protective role in host defense against viral infections." (PMID 34117371, 2021). "In 2017, D’Angelo also demonstrated that LPS, TNF-α, and viral infection, induce robust inflammatory responses in naturally differentiated cells." (PMID 34094036, 2021). "Investigation of the mechanisms and consequences of TLR2 signaling have primarily focused on pathogen-specific induction of type I IFNs and TNF, largely in response to S. aureus exposure or viral infection." (PMID 34755600, 2021). "M-CSF MФ produced low levels of TNF-α in response to virus infection alone and also in response to LCMV infection followed by R848 stimulation." (PMID 33331816, 2021). "TNF is locally induced early after virus infection and enhances its own expression together with other pro-inflammatory cytokines and also the secretion of chemokines that promote the recruitment and activation of leukocytes." (PMID 34451529, 2021). "The ‘viral processes’ term was significantly enriched in our DIA analysis, in line with literature reporting the involvement of TNF-mediated ubiquitination during viral infection." (PMID 33431886, 2021). "At the same time, IL-1β, IL-4, IL-6, IFN-γ, GM-CSF, and TNF-α activate inflammatory effector mechanisms typical of a viral infection." (PMID 34831403, 2021). "Bacterial or viral infection activates NF-κB through toll-like receptors, resulting in the production of proinflammatory cytokines including TNF-α, IL-1β, and IL-6." (PMID 34393799, 2021). "The increasing plasma cytokines (IL-1β/2R/6/8/10 and TNF-α) confirmed the cytokine storm following the virus infection." (PMID 33625490, 2021).